REN (renin)
Diseases named in the same sentence as REN in open-access papers (continued):
Sharing a sentence is not in itself a finding about the gene and the disease.
Hypertension (continued). "Antenatal glucocorticoid exposure causes offspring hypertension, coinciding with the upregulation of renin, PRR, ACE, and AT1R expression." (PMID 38542273, 2024). "An impaired sodium excretion leading to fluid retention and increased activity of the renin-angiotensin- aldosterone system (RAAS) are the major pathogenic factors in the development of hypertension in DKD3." (PMID 38424466, 2024). "Periodontitis-induced inflammation and oxidative stress can lead to arterial stiffness, vascular dysfunction, and hypertension, and can activate the renin-angiotensin system, causing the release of Angiotensin II." (PMID 39139765, 2024). "All 6 patients with hypertension suffered from grade 2 hypertension and hypokalaemia caused by the increased production of renin due to stenosis of the renal arteries." (PMID 38243321, 2024). "A case-control study in Han Chinese showed that the dominant model (CC vs. CT + TT) of rs1894111 polymorphism in the ADRBK1 (GRK2) gene is associated with low-renin hypertension." (PMID 38961282, 2024). "This is similar to the findings of another study in which Grk2 knockdown in mice exacerbates kidney injury and causes spontaneous hypertension, accompanied with over-activation of the renal renin-angiotensin system (RAS) and AT1R signaling." (PMID 38961282, 2024). "The renin-aldosterone angiotensin system, involved in hypertension, has been associated with AD pathology and neurotoxic reactive oxygen species, where angiotensin binds to specific angiotensin-1 receptors in the hippocampus and cerebral cortex." (PMID 38290839, 2024). "This would be of interest given that data from a large observational study suggested that patients with hypertension and low renin have an increased cardiovascular risk profile compared to those with normal renin." (PMID 38200100, 2024). "REN SNP lacks association with hypertension in this study, as well as in other studies conducted in Japanese and Malaysian populations." (PMID 38935682, 2024). "PA arises from the autonomic production of aldosterone in the adrenal glands, which causes hypertension with an increased ratio of aldosterone/renin and hypokalaemia." (PMID 38780511, 2024). "Partial occlusion of the renal artery causes an increase in renin production, which in turn causes hypertension and decreased blood flow to the uterus and placenta, resulting in fetal growth restriction." (PMID 38363321, 2024). "Classification based on renin levels can help differentiate the pathophysiological causes of hypertension." (PMID 38410670, 2024). "First, uric acid causes hypertension in the rat via activating the renin-angiotensin system inducing vascular smooth muscle cell proliferation, oxidative stress, and renal arteriolopathy." (PMID 38356958, 2024). "One of the major pathophysiological mechanisms suggested for the association of hypertension with worse outcomes in COVID-19, is based on the renin-angiotensin-aldosterone system(RAS)." (PMID 39163410, 2024). "Possible mechanisms linking LTPA and lower hypertension risk include the reduction of body weight, sympathetic activity, renin activity, insulin resistance, and improvement of vascular endothelial function and arterial stiffness." (PMID 38163915, 2024). "The pathophysiology of hypertension consists of the activation of ACE2 that causes an increase in the activity of the renin–angiotensin–aldosterone system (RAAS), resulting in vasoconstriction, which causes organ damage." (PMID 38905361, 2024). "Lastly, rs1014754 positively associated with kallistatin, whereas rs17677724 negatively associated with renin in the Fenland study, suggesting a counterregulatory response to high blood pressure." (PMID 39011893, 2024). "At this age, hypertensive disorders related to pregnancy and female hormonal alterations (e.g., pre-menopausal state) that interact with the renin-angiotensin-aldosterone system can be associated with higher blood pressure." (PMID 38510349, 2024).
Hypertension (continued). "Activation of the renin-angiotensin system is a major cause of many common pathological conditions, including hypertension, heart failure, and renal disease." (PMID 36803883, 2023). "Renin-angiotensin stimulation and vitamin D deficiency are direct factors to release high levels of ROS, which is a risk factor in hypertension." (PMID 36839279, 2023). "Renin expression has been associated with elevated blood pressure and a higher risk of hypertension." (PMID 37571339, 2023). "Obesity-related hypertension is associated with increased salt sensitivity, increased sympathetic nervous system activity, activation of the renin-angiotensin-aldosterone system(RAS), and aldosterone secretion by adipose tissue." (PMID 37908019, 2023). "Overactivation can cause vasoconstriction and activation of the renin-angiotensin-aldosterone system, promoting the development of hypertension." (PMID 37089694, 2023). "This is accompanied by endothelial dysfunction and increased renin-angiotensin system expression, aggravating atherosclerotic processes, hypertension and cardiovascular risk." (PMID 37943388, 2023). "IPTH is linked to the renin–angiotensin–aldosterone system (RAAS) as a probable mechanism of hypertension and ICH." (PMID 37034079, 2023). "The initial drug of choice is an angiotensin-converting enzyme (ACE) inhibitor or angiotensin receptor blocker (ARB) to treat hypertension by targeting the underlying pathogenesis in the activation of the renin-angiotensin-aldosterone system." (PMID 37038580, 2023). "Epidemiological and clinical studies demonstrated an association between inadequate exposure to sunlight, vitamin D deficiency, and hypertension or increased plasma renin activity." (PMID 36902110, 2023). "In conclusion, DOCA-salt is a model of low-renin hypertension and hypermetabolism, and this model is associated with and dependent upon induction of the brain RAS and activation of the angiotensin AT1R within specific brain regions and cell types." (PMID 37293629, 2023). "Dysregulation of the renin-angiotensin-aldosterone system has not only been implicated in the pathophysiology of hypertension, but it also favors T2DM." (PMID 37894687, 2023). "According to previous research, even a short-term acute vitamin D shortage can cause hypertension and affect the parts of the renin-angiotensin system that cause kidney damage." (PMID 36851366, 2023). "The renin–angiotensin–aldosterone system (RAAS) regulates body hypertension and fluid balance which causes CVD." (PMID 37324400, 2023). "To establish the causal role of renin in Prdm6fl/+ SM22-Cre mice hypertension we fed them a high-salt diet and simultaneously treated them with the renin inhibitor aliskiren by daily oral gavage (50 mg/kg)." (PMID 36602864, 2023). "This hypertension is caused by the external compression of the kidney by a chronic subcapsular hematoma that activates the renin-angiotensin-aldosterone system (RAAS) system." (PMID 38249211, 2023). "Arterial hypertension is associated with the triggering of the renin–angiotensin system, leading to left ventricle fibrosis and worse cardiovascular outcomes." (PMID 37692038, 2023). "Cardiovascular‐renal disease (CvRD), a condition in which both cardiac and renal dysfunction negatively affect each other, is caused by sympathetic activation, renin‐angiotensin‐aldosterone system activation, hypertension, and GFR reduction." (PMID 36852471, 2023). "Supressed plasma renin in patients with primary hypertension is thought to be an indirect marker of sodium-induced volume expansion which is associated with more severe hypertension and hypertension-mediated organ damage." (PMID 35414109, 2023). "Elevated levels of renin synthesis and secretion are directly or indirectly stimulated by T3, and in hyperthyroidism, other hormonal factors associated with hypertension, such as endothelin-1, were also found to be increased." (PMID 38174182, 2023).
Hypertension (continued). "The mechanisms underlying vitamin D deficiency-related hypertension include increased renin expression, hypocalcemia, and hyperparathyroidism." (PMID 37273529, 2023). "Many mechanisms are involved in causing hypertension, i.e., via calcium channels, alpha and beta receptors, and the renin-angiotensin system (RAS)." (PMID 37389408, 2023). "Hypertension and hypercholesterolemia have been suggested to be linked through the involvement of the renin–angiotensin system." (PMID 37892538, 2023). "The central axis of hypertension control is associated with the renin-angiotensin-aldosterone system (RAAS) from the signaling of angiotensin II-converting enzyme (ACE2) receptors, the primary ligand of the S protein of SARS-CoV-2." (PMID 38131441, 2023). "Heavy alcohol consumption increases the risk of hypertension by altering the heart or vascular smooth muscle and stimulating the sympathetic nervous system or the renin-angiotensin-aldosterone (RAS) system." (PMID 37273529, 2023). "Hypertension in premature individuals was also associated with endothelial dysfunction and changes in the renin–angiotensin–aldosterone (RAAS) system, the sympathetic nervous system and renal alterations." (PMID 37510630, 2023). "In the surgical hypertension model used, the kidney, whose blood flow decreases, secretes renin, which causes increased angiotensin II (ANG II) generation and as a result raises blood pressure." (PMID 37582694, 2023). "It reported that a lower plasma renin activity and higher plasma aldosterone concentration in patients with hypertension were associated with a higher white matter lesion load." (PMID 37568223, 2023). "Ischemia in hypertension causes numerous changes in various organs, such as the renin-angiotensin system (RAS), a critical regulator of systemic vascular resistance and blood pressure." (PMID 37664430, 2023). "Arterial hypertension is linked to DNA damage via the generation of oxidative stress, in which an upregulated renin–angiotensin–aldosterone system plays a crucial role." (PMID 38001818, 2023). "Page kidney or Page phenomenon is a rare cause of hypertension that results from external compression of the kidney and renin-angiotensin-aldosterone system activation." (PMID 37575746, 2023). "Renal parenchymal lesions resulting from intrarenal urine reflux predispose the patient to hypertension by renin-angiotensin system activation, representing one of the most common causes of hypertension in children." (PMID 36983379, 2023). "Although the exact underlying mechanisms connecting hypertension with the increased risk of cancer remain to be clarified, the renin-angiotensin-aldosterone system (RAAS) seems to be a major connecting factor in hypertension, CVD, and cancer nexus." (PMID 37520844, 2023). "Vision loss in diabetic retinopathy features damage to the blood–retinal barrier and neovascularization, with hypertension and the renin–angiotensin system (RAS) having causal roles." (PMID 36768656, 2023). "Hypertension originating from kidney disease is associated predominately with the renin-angiotensin system of blood pressure control." (PMID 37368616, 2023). "Meanwhile, the incidence of hypertension with erythropoietin use is estimated to be approximately 10% to 15% and is associated with NO, endothelins, and the sympathoadrenal and renin-angiotensin pathways." (PMID 37919317, 2023). "Increased understanding of the causes and consequences of these low-renin forms of hypertension is necessary to further the development of new efficacious, safe, and personalized therapeutic approaches." (PMID 37293629, 2023). "It is known from the literature that vitamin D deficiency can lead to high blood pressure and affects the renin–angiotensin system." (PMID 38068901, 2023). "Genetic polymorphisms in the renin-angiotensin system have been associated with an increased risk of hypertension and resistance to antihypertensive medications." (PMID 37416924, 2023).
Hypertension (continued). "The low vitamin D3 (mainly the bioactive dihydroxylated form) has been revealed to associate with increased renal renin and angiotensin II production, consequently elevating blood pressure or developing essential hypertension." (PMID 37528997, 2023). "Insulin resistance is associated with stimulating both the renin–angiotensin system and sympathetic system activities, contributing to increased renal sodium reabsorption, fluid retention, and hypertension." (PMID 35455055, 2022). "Hypertension forms typically associated with marked activation of the renin-angiotensin-aldosterone system, such as unilateral renal artery stenosis, are often associated with hypokalemia." (PMID 35627493, 2022). "Since DOC accumulates upstream of the block by the failed enzyme, this mineralocorticoid causes low-renin hypertension, although it is slightly less potent than ALDO." (PMID 36589849, 2022). "Hypertension is conventionally associated with a neurohormonal activation from the sympathetic nervous and the renin-angiotensin-aldosterone systems (RAAS)." (PMID 35360022, 2022). "Excessive fat accumulation activates the renin‐angiotensin‐aldosterone system and the sympathetic nervous system, followed by hypertension, which is the major risk factor for CVD." (PMID 35212175, 2022). "Hypertension causes activation of the renin–angiotensin system and inhibition of nitric oxide synthesis, which promote endothelial dysfunction and the proliferation of vascular smooth muscle cells." (PMID 36148448, 2022). "The kidneys play an important role in blood pressure regulation through the renin-angiotensin-aldosterone axis, and impairment of kidney function can cause hypertension, which is an important risk factor for a range of cardiovascular outcomes." (PMID 35488232, 2022). "As expected, 2K1C hypertension in WT mice was associated with increases in renin mRNA expression in the clipped left kidney, and circulating and kidney cortical Ang II levels, accompanied by significant tubulointerstitial injury in the clipped kidney." (PMID 36555438, 2022). "A large aneurysmal renal arteriovenous fistula (AVF) can cause hypokalaemic hypertension due to activation of renin-aldosterone system due to steal effect from renal parenchyma." (PMID 35622189, 2022). "This large-scale cohort study, over 12 years, found that hypertension occurred more in the low-renin group, among community-dwelling Koreans, and the genetic predisposition influenced the future hypertension incidence, according to renin concentration." (PMID 35448080, 2022). "In a rat model, hyperuricemia was shown to induce primary arteriolopathy of the preglomerular vasculature of the kidneys by stimulating vascular smooth muscle cells, thereby causing activation of the renin-angiotensin system and hypertension." (PMID 36145212, 2022). "Hypertension in people with type 2 diabetes is generally associated with expanded plasma volume, increased peripheral vascular resistance and low renin activity." (PMID 34979961, 2022). "The epigenetic regulation of the renin–angiotensin–aldosterone system (RAAS) potentially plays a role in the pathophysiology underlying the high burden of hypertension in sub-Saharan Africans (SSA)." (PMID 36457109, 2022). "The mechanistic basis of RC-associated hypertension is not fully understood, potentially involving vascular damage, inflammation, oxidative stress, the renin–angiotensin system, and insulin resistance." (PMID 35222285, 2022). "Pseudohypoaldosteronism type II (PHA II) is a Mendelian disorder, featuring hyperkalemic acidosis and low plasma renin levels, typically associated with hypertension." (PMID 35093948, 2022). "Many studies have been described the association of vitamin D with hypertension and cardiovascular risk, predominantly with its crucial regulator effects throughout elevated Renin-angiotensin-aldosterone system (RAAS) activity." (PMID 35930297, 2022).
Hypertension (continued). "Firstly, the tumor locally compresses the renal artery and its branches, activates the renin-angiotensin-aldosterone system, causes peripheral vascular contraction, water and sodium retention, and leads to hypertension." (PMID 36229776, 2022). "OSA-related hypertension is usually attributed to increased diastolic blood pressure caused by sympathetic activation, which stimulated the renin angiotensin-aldosterone system to increase vascular resistance and cardiac output, causing hypertension." (PMID 35277151, 2022). "Cx40-deficient mice exhibit hyperreninemia and hypertension because of overactivation of the renin–angiotensin–aldosterone system." (PMID 36555574, 2022). "The increase of hs-CRP can damage vascular endothelial cells, affect the level of renin-angiotensin, and cause the occurrence of hypertension." (PMID 35813436, 2022). "Further prospective studies, including changes in renin level and other comorbidities, which can affect the incident hypertension, are needed to demonstrate the genetic polymorphisms as a predictive marker of hypertension more clearly." (PMID 35448080, 2022). "Patients are diagnosed based on a clinical case finding with hypertension and an increased aldosterone to renin ratio (ARR), often associated with hypokalemia." (PMID 36057693, 2022). "It plays a key role in diabetes, renal, and cardiovascular disease by counterbalancing the ACE/renin angiotensin aldosterone system which is associated with sodium and water retention, vasoconstriction, hypertension, and accelerated thrombosis." (PMID 35962323, 2022). "This feature is also common in normotensive and hypertensive black subjects and in patients with essential low renin hypertension, who usually have good control of hypertension and reduced cardiovascular risk when treated with MR blockers." (PMID 36613755, 2022). "Multiple mechanisms are related to renal damage caused by UA, including contributions to the development of hypertension, activation of the renin-angiotensin-aldosterone system (RAAS), inflammation, and oxidative stress reactions." (PMID 35034618, 2022). "In studies concerning OSA in humans, intermittent hypoxia led to an activation of the renin-angiotensin system, sympathetic nervous system, endothelial dysfunction and thus an increased risk for hypertension." (PMID 36619949, 2022). "Typical clinical features include severe hypertension, secondary hyperaldosteronism, hypokalaemia and metabolic alkalosis caused by the overproduction of renin." (PMID 35303838, 2022). "In this study, there are two SNPs (rs11726091 and rs8137145) in regions associated with high renin level and hypertension." (PMID 35448080, 2022). "Evidence from previous studies has suggested that dysregulation of the Renin-Angiotensin System during hypertension is associated with increased oxidative stress and endothelial dysfunction." (PMID 36232649, 2022). "Physical exercise effectuates vascular resistance and ultimately leads to vasodilation by altering the renin-angiotensin-aldosterone system, thereby reducing the risk of hypertension." (PMID 36268382, 2022). "The T-allele frequency is also higher among hypertensive patients, and the polymorphism is, in general, associated with low renin hypertension." (PMID 36077181, 2022). "This study aimed to examine the genetic predisposition of the plasma renin concentration influencing future hypertension incidence." (PMID 35448080, 2022). "The renin-angiotensin system is involved in the physiopathology of stroke and has an essential impact on hypertension as a risk factor." (PMID 35409237, 2022). "Specifically, ETB exerts natriuretic functions, and collecting duct-specific deficiency of ETB accordingly causes systemic hypertension with decreased urinary aldosterone excretion and plasma renin activity." (PMID 35757687, 2022).